AZU1 (azurocidin 1)
Description:
This is a neutrophil granule-derived antibacterial and monocyte- and fibroblast-specific chemotactic glycoprotein. Binds heparin. The cytotoxic action is limited to many species of Gram-negative bacteria; this specificity may be explained by a strong affinity of the very basic N-terminal half for the negatively charged lipopolysaccharides that are unique to the Gram-negative bacterial outer envelope. It may play a role in mediating recruitment of monocytes in the second wave of inflammation. Has antibacterial activity against the Gram-negative bacterium P.aeruginosa, this activity is inhibited by LPS from P.aeruginosa. Acting alone, it does not have antimicrobial activity against the Gram-negative bacteria A.actinomycetemcomitans ATCC 29532, A.actinomycetemcomitans NCTC 9709, A.actinomycetemcomitans FDC-Y4, H.aphrophilus ATCC 13252, E.corrodens ATCC 23834, C.sputigena ATCC 33123, Capnocytophaga sp ATCC 33124, Capnocytophaga sp ATCC 27872 or E.coli ML-35. Has antibacterial activity against C.sputigena ATCC 33123 when acting synergistically with either elastase or cathepsin G.
Synonyms: HBP; hHBP; AZU; CAP37; AZAMP; NAZC; HUMAZUR
Tractability: Antibody: UniProt places it where antibodies can reach, with high confidence; its Gene Ontology location is reachable by antibodies, with high confidence; UniProt predicts a signal peptide or a membrane-spanning region. PROTAC: its protein half-life has been measured.
Gene: Protein-coding gene on chromosome 19 (825,097 to 832,018, forward strand). Ensembl gene ENSG00000172232.
Subcellular location: Cytoplasmic granule membrane
Subcellular location (Human Protein Atlas): Vesicles; Predicted to be secreted
Pathways (Reactome):
Immune System: Neutrophil degranulation
Gene Ontology:
Molecular function: heparan sulfate proteoglycan binding; heparin binding; peptidase activity; protein binding; serine-type endopeptidase activity; toxic substance binding
Biological process: antimicrobial humoral response; cell chemotaxis; defense response to virus; glial cell migration; intracellular signal transduction; microglial cell activation; monocyte extravasation; neutrophil-mediated killing of bacterium; positive regulation of cell adhesion; positive regulation of fractalkine production; positive regulation of interleukin-1 beta production; positive regulation of MHC class II biosynthetic process; positive regulation of phagocytosis; positive regulation of tumor necrosis factor production; proteolysis; cellular extravasation; defense response to Gram-negative bacterium; induction of positive chemotaxis; inflammatory response; macrophage chemotaxis; monocyte activation; negative regulation of apoptotic process; phospholipase C-activating G protein-coupled receptor signaling pathway; protein maturation; regulation of vascular permeability
Cellular component: azurophil granule; azurophil granule membrane; extracellular exosome; extracellular region; membrane; azurophil granule lumen
Genetic constraint (gnomAD): Loss-of-function variants: 21 observed, 17.2 expected, observed/expected ratio (o/e) 1.22, 90% interval 0.86 to 1.73. The upper end of that interval is the gene's LOEUF score, 1.73, which puts it in group 6 of 6, group 1 being the genes least tolerant of losing a copy. Missense variants: 379 observed, 346.89 expected, observed/expected ratio (o/e) 1.09, 90% interval 1 to 1.19. Synonymous variants: 178 observed, 149.43 expected, observed/expected ratio (o/e) 1.19, 90% interval 1.05 to 1.35.
Homologues: Orthologues: chimpanzee AZU1 (98% identical), macaque AZU1 (89% identical), pig AZU1 (66% identical). Paralogues in human: CTSG (36% identical), GZMB (34% identical), GZMH (33% identical), CMA1 (31% identical), KLK13 (29% identical), KLK6 (28% identical).
Diseases named in the same sentence as AZU1 in open-access papers:
AZU1 is named in the same sentence as 75 diseases in open-access papers, as found by Europe PMC text mining. Sharing a sentence is not in itself a finding about the gene and the disease. The quoted sentences say what the papers report.
Sepsis (43 papers, 2012 to 2026). Sepsis is defined as life-threatening organ dysfunction caused by a dysregulated host response to infection. "As a multifunctional protein, AZU1 has been shown to be associated with various diseases, including sepsis, acute lung injury, and acute respiratory distress syndrome." (PMID 40722939, 2025). "In our study, AZU1 was found to have a limited prognostic value in septic patients, which contrasts with findings from other studies reporting notably higher plasma AZU1 levels in sepsis associated with organ dysfunction." (PMID 39202614, 2024). "Overall, these findings underscore the potential of DNA methylation as biomarkers in sepsis, particularly for AZU1, MPO, SERPINA1, and SLX4, which show strong correlations with clinical indicators of severity and inflammation." (PMID 39926115, 2024). "Based on their high differential methylation levels and their role in the immune functions identified, four genes (SERPINA1, AZU1, MPO and SLX4) were selected for further validation, supported by available evidence of their biological roles in sepsis." (PMID 39926115, 2024). "SERPINA1, AZU1, MPO and SLX4 genes stand out for their correlation with inflammation and severity and have potential as biomarkers for diagnosing sepsis and predicting poor prognosis." (PMID 39926115, 2024). "In 26 upregulated OCRGs in AIs, the upregulation of two regulators, SERPINA1 and AZU1, was shared among acute respiratory distress syndrome (ARDS), sepsis, and trauma; upregulation of CD24 and FKBP8 was shared among ARDS and trauma; and upregulation of GRN was shared between sepsis and trauma." (PMID 34368262, 2021).
COVID-19 (7 papers, 2020 to 2025). A disease caused by infection with severe acute respiratory syndrome coronavirus 2. "The neutrophil proteases PRTN3 (proteinase-3) and MPO (myeloperoxidase) and the neutrophil-derived protein AZU1 were associated with severe disease, indicating that neutrophil activation and degranulation are features of severe COVID-19." (PMID 33704068, 2021). "For instance, while reducing the correlation between DEGs including IL10, CXCL8, NFKB1, ARG1, and SOD2, new strong associations appeared between ELANE, DEFA4, AZU1, CTSG, and LCN2, with an overall tendency to higher relationships amid neutrophil-mediated immunity genes in COVID-19 patients." (PMID 35269470, 2022). "In addition, targeting other neutrophil proteins like Azurocidin (AZU1) and cathepsin G (CTSG) that are elevated in nasopharyngeal swaps of COVID-19 patients, as well as the inhibition of NET formation, have been suggested to alleviate SARS-CoV-2 symptoms." (PMID 35269470, 2022). "Furthermore, the genes ELANE, AZU1, MPO, PRTN3, CTSG, and TCN1 were shown to be significantly altered in patients with COVID-19, and our automatically prepared knowledge base highlights all of them as associated with COVID-19 with “medium” or “low” confidence." (PMID 33055059, 2020). "Indeed, it has been suggested that, with other proteins such as Azurocidin 1, ITIH4 could help in avoiding the SARS-CoV-2 complete elimination, in the bodies of long-term persistent COVID-19 patients." (PMID 39594201, 2024).
bacterial meningitis (4 papers, 2014 to 2022). Inflammation of the membranes surrounding the brain and spinal cord due to a bacterial infection. "Our study also demonstrated that AZU1 could be a potential biomarker for the diagnosis of hydrocephalus in bacterial meningitis." (PMID 36052359, 2022).
breast carcinoma (4 papers, 2010 to 2019). "TACC2 (AZU-1) is a putative tumor suppressor in breast cancer." (PMID 21113414, 2010).
viral infection (3 papers, 2013 to 2023). "Several differentially expressed genes between the two trajectories (CTSG, PRC1, DEFA4, KIF15, TCEAL9, HMMR, CEP55, and AZU1) were overexpressed in patients with severe viral infection, but not in those with non-severe viral infection compared to HCs." (PMID 33765435, 2021).
prostate carcinoma (2 papers, 2017 to 2019). A carcinoma that arises from epithelial cells of the prostate gland. "AZU1 expression, which is upregulated in MDS, CMML and AML, has been linked with certain other myeloproliferative neoplasms, as well as renal cell and prostate cancer." (PMID 31870430, 2019).
adenoma (1 paper, 2024). A neoplasm arising from the epithelium. "In this context, we highlight that AZU1 has also been previously observed as elevated in the stools of adenomas and CRC patients, as well as PRTN3, found in polyps and CRC tissues." (PMID 38612533, 2024).
asthma (1 paper, 2023). "OS biomarkers MDA, FRAP, protein carbonyls, and peroxynitrite, and inflammation biomarkers ILC2/3, MMP-12, CXCL8, neutrophil elastase, AZU-1, and PPBP were found to associate with asthma in smokers, but not in nonsmokers." (PMID 37367073, 2023).
empyema (1 paper, 2019). An accumulation of pus in a body cavity, usually the pleural space. "Otherwise, the serum levels of BPI and AZU1 were similar between CPPE, empyema, and UPPE." (PMID 31215423, 2019).
endometriosis (1 paper, 2017). The growth of functional endometrial tissue in anatomic sites outside the uterine body. "Nine proteins were reduced in endometriosis, including Azurocidin 1, an important inflammatory mediator, cysteine-rich secretory protein 3 (CRISP-3) and Heat shock protein beta-1 (HSPB1)." (PMID 28174513, 2017).
Hydrocephalus (1 paper, 2022). Hydrocephalus is an active distension of the ventricular system of the brain resulting from inadequate passage of CSF from its point of production within the cerebral ventricles to its point of absorption into the systemic circulation. "The expression levels of AZU1 in the hydrocephalus group were significantly different from these in the other groups." (PMID 36052359, 2022). "In our study, AZU1 levels in CSF from the hydrocephalus group were significantly different from these in the other two groups, this indicating that AZU1 may be a potential protein biomarker for hydrocephalus in BM." (PMID 36052359, 2022).
leukemia (1 paper, 2022). A malignant (clonal) hematologic disorder, involving hematopoietic stem cells and characterized by the presence of primitive or atypical myeloid or lymphoid cells in the bone marrow and the blood. "Importantly, some of these genes have already been reported in relation to CML (e.g., AURKB, AZU1, HLA-B, HLA-DMB, PF4) and others have been found to play important roles in different leukemias (e.g., CDCA3, RPL18A, PRG3, TLX3)." (PMID 35008420, 2022).
Parkinson disease (1 paper, 2025). A progressive degenerative disorder of the central nervous system characterized by loss of dopamine producing neurons in the substantia nigra and the presence of Lewy bodies in the substantia nigra and locus coeruleus. "Other notable observations include the downregulated levels of OSM, MNDA, AZU1 and MMP9, which are well-known neuroinflammatory markers, proven in several Parkinson’s disease models." (PMID 39816194, 2025).
periodontitis (1 paper, 2023). An acute or chronic inflammatory process that affects the tissues that surround and support the teeth. "Azurocidin 1 has inhibitory activity during periodontitis, so its variable level can cause different pathological states." (PMID 36949424, 2023).
plaque psoriasis (1 paper, 2021). "Increased CCL18, CHI3L1 and AZU1 levels were detected in plasmas from plaque psoriasis, but we could not confirm their association with anti-CA IgA levels, which remains a limitation of the study." (PMID 33546306, 2021).
Pleural effusion (1 paper, 2017). The presence of an excessive amount of fluid in the pleural cavity. "Four novel upregulated candidates (BPI, NGAL, AZU1, and calprotectin) were selected and further verified using enzyme-linked immunosorbent assays (ELISAs) on 220 patients with pleural effusions due to different causes." (PMID 28642494, 2017). "The four novel proteins (BPI, NGAL, AZU1, and calprotectin) identified in pleural effusion fluid specimens were further verified by ELISA in samples from 176 patients with different pleural effusion aetiologies." (PMID 28642494, 2017). "Among the five types of pleural effusions, the protein levels of BPI, NGAL, AZU1, and calprotectin in CPPE were highest and estimated (expressed as the mean values ± s.e.m)." (PMID 28642494, 2017). "According to the proteomics data and bioinformatics analysis, four proteins were selected as potential biomarker candidates, including BPI, NGAL, AZU1, and calprotectin, and their roles in pleural effusions have not been addressed before." (PMID 28642494, 2017).
Sciatica (1 paper, 2021). Pain in the lower back and hip radiating in the distribution of the sciatic nerve. "AZU1, BPI, TCF7L2, and WFIKKN1 were upregulated in sciatica patients, while ANGPTL4, CRP, EREG, FAM19A4, FGF1, LOC100129216, PLXNB1, RLN1, and RXFP2 were downregulated." (PMID 34925462, 2021).
vasculitis (1 paper, 2018). "It is remarkable that AZU1 and VCAM1 hypomethylated in their genes presumably combine their partners (e.g., chemokines and adhesion receptors) to trigger vasculitis that can be observed in most of autoimmune conditions including RA and SLE." (PMID 30159339, 2018).
tumor (18 papers, 2010 to 2026). "They found that tumor tissue-derived sEVs were rich in azurocidin 1 (AZU1) and effectively altered vascular endothelial cell layer permeability." (PMID 37469514, 2023). "Interestingly, comprehensive protein cargo analysis by LC/MS revealed that azurocidin (AZU1) was significantly enriched in tumor‐derived exosomes and these may even play a functional role in driving metastatic dissemination." (PMID 33194717, 2020). "Among stromal FOV, GPX3 is the most significant downregulated gene in IO-exposed tumor cells (FDR < 0.001), and AZU1 was found to be downregulated in regulatory T cells (FDR < 0.001) and fibroblasts (FDR < 0.001)." (PMID 39639369, 2024). "The total protein levels of LTF, LCP1, AZU1, and ENO1 were all shown to be downregulated in tumor tissues." (PMID 37304069, 2023). "In summary, elevated AZU1 expression appears to be observable in a subgroup of cases, irrespective of the tumor recurrence time." (PMID 33820913, 2021). "AZU1 and KIR3DL2 were potentially related with tumor immune microenvironment." (PMID 32732980, 2020). "The findings imply that LTF, AZU1, and ENO1 are related to tumor grade, while LCP1 is not substantially different among tumor stages." (PMID 37304069, 2023).
infection (9 papers, 2007 to 2025). The state of being infected such as from the introduction of a foreign agent such as serum, vaccine, antigenic substance or organism. "Elevated AZU1 levels effectively distinguished patients with a healthy condition from those suffering from infection." (PMID 38357095, 2024). "AZU1 holds promise as a serum biomarker for early infection detection and successful treatment." (PMID 38357095, 2024). "Statistically significant protein alterations of PRTN3, MPO, ELANE, CTSG, and AZU1 dysregulation is important in the early phases of infection and may be targets for anti-SARS-CoV-2 therapeutics." (PMID 33079950, 2020).
bacterial infections (6 papers, 2020 to 2024). "Two of these proteins, S100A9 and AZU1, are associated with neutrophils and play a key role in the host’s defense against bacterial infections." (PMID 38397935, 2024).
cancer (6 papers, 2011 to 2024). A tumor composed of atypical neoplastic, often pleomorphic cells that invade other tissues. "In addition, RCC-EVs were studied for their modulation of vascular permeability affecting metastatization, thanks to their enrichment in the azurocidin protein (AZU1) being significantly higher in serum and cancer-tissue-derived EVs from ccRCC patients compared to those from healthy donors." (PMID 37372161, 2023). "Among cancer and precancerous lesions glycoproteins, we further highlight seven glycoproteins found in high-grade dysplasia as well as cancer (IGHG1, CPA2, MYH2, AZU1, PRTN3, CA1, SMPDL3B), holding potential for non-invasive detection of aggressive traits." (PMID 38612533, 2024).
adenocarcinoma (1 paper, 2014). A common cancer characterized by the presence of malignant glandular cells. "These are azurocidin 1 (DAA27509.1), pancreatic adenocarcinoma upregulated factor (PAUF) (XP_002697974), common salivary protein BSP30b (P79125), and serum amyloid P-component (Q3T004)." (PMID 24721702, 2014).
inflammation (1 paper, 2023). Aberrant reaction of the microcirculation characterized by movement of fluid and leukocytes from the blood into extravascular tissues. "Higher levels of Matrix metallopeptidase (MMP-12), C-X-C motif chemokine ligand-8 (CXCL8), neutrophil elastase, azurocidin 1 (AZU-1), and pro-platelet basic protein (PPBP) were observed in the sputum of ex-smoking asthmatics, which are linked to neutrophilic inflammation." (PMID 37367073, 2023).
AZU1 also shares sentences with these, for which no sentence is quoted: acute kidney injury (4 papers); acute respiratory distress syndrome (4); endothelial dysfunction (4); hepatoma (4); Alzheimer disease (3); cardiac arrest (3); infectious disease (3); pneumonia (3); acute respiratory failure (2); dementia (2); meningitis (2); myocarditis (2); systemic lupus erythematosus (2); viral pneumonia (2); acute pancreatitis (1); adult-onset Still disease (1); anemia (1); Arthritis (1); atherosclerosis (1); Atrophy (1); Autoimmunity (1); bacterial sepsis (1); cardiogenic shock (1); Cardiovascular Diseases (1); chronic obstructive pulmonary disease (1); corneal infection (1); cystic fibrosis (1); diabetes nephropathy (1); dysplasia (1); edema (1).
A further 21 diseases each share a sentence with AZU1 in 1 paper.